OSM (oncostatin M)
Diseases named in the same sentence as OSM in open-access papers (continued):
Sharing a sentence is not in itself a finding about the gene and the disease.
psoriasis vulgaris (1 paper, 2023). Plaque psoriasis is the most common presentation of psoriasis. "In fact, expression of OSM is enhanced in AD and psoriasis vulgaris lesions, although the mechanisms underlying this upregulation are unknown." (PMID 38035099, 2023). "The expression of OSM was substantially elevated in skin lesions from AD and psoriasis vulgaris patients, consistent with a previous report." (PMID 38035099, 2023). "To elucidate the contributions of OSM signaling to AD and psoriasis vulgaris, we first examined if OSM expression is upregulated in lesions compared to healthy skin tissue." (PMID 38035099, 2023). "We confirmed overexpression of OSM in skin lesions of patients with AD and psoriasis vulgaris." (PMID 38035099, 2023). "Further, OSM expression is enhanced in the skin lesions of AD and psoriasis vulgaris patients." (PMID 38035099, 2023).
pustular psoriasis (1 paper, 2024). "This autoinflammatory positive feedback loop is driven by elevated levels of IL1 and OSM which are sufficient to induce BIT in murine BCC allografts and are reminiscent of autoinflammatory skin disorders like pustular psoriasis that are associated with neutrophilic infiltrates." (PMID 39289380, 2024).
retinal diseases (1 paper, 2024). "The increased expression of IL-6 and OSM in retinal diseases, such as DR and AMD, may reflect a failure of anti-inflammatory pathways to properly regulate chronic low-grade inflammation, which is a key feature in the progression of these diseases." (PMID 39759107, 2024).
rosacea (1 paper, 2025). A chronic erythematous skin disorder that affects the face. "It was found that rosacea is closely associated with a chronic inflammatory state, particularly with significantly elevated expression of genes such as IL6, OSM, and TNF‐α." (PMID 39823143, 2025). "In addition, RT‐qPCR analysis of inflammatory factors in skin tissue revealed that the expression levels of IL‐6, OSM, and TNF‐α were significantly higher in rosacea patients than in the healthy control group." (PMID 39823143, 2025).
scrapie (1 paper, 2021). A fatal disease of the nervous system in sheep and goats, characterized by pruritus, debility, and locomotor incoordination. "High-density qRT-PC studies investigating different times of the disease progression revealed overexpression of inflammatory genes Il1rn [IL-1Ra], Ccl8 [CCL8/MCP-2], Tnfsf11 [Tnfsf11/RANKL], and Osm [OSM]) at the preclinical stage in scrapie strain 22L-infected mice)." (PMID 33801117, 2021).
squamous cell carcinoma (1 paper, 2020). A carcinoma arising from squamous epithelial cells. "In squamous cell carcinoma, OSMR overexpression activates cell-autonomous feed-forward signaling that induces further expression of OSMR and OSM, leading to a pro-malignant phenotype." (PMID 32248843, 2020).
staphylococcus aureus infection (1 paper, 2024). An infectious process in which the bacteria Staphylococcus aureus is present. "In the early stages of Staphylococcus aureus infection, the expression levels of several genes encoding pro-inflammatory molecules (IL8, IL1B, OSM, and CXCR1, etc.)show a dramatic increase, with the expression of IL8 increasing up to 8196-fold." (PMID 39065061, 2024).
thymic atrophy (1 paper, 2011). "Work from this laboratory has previously shownthat injection of IL-6, as well as IL-6 family members LIF and OSM, actively induceacute thymic atrophy within three days." (PMID 21437240, 2011).
type 2 diabetes (1 paper, 2015). "We demonstrated that OSM mRNA and protein levels were elevated in AT of both ob/ob mice and high-fat diet (HFD)-fed B6 mice; these rodent models are both used to study obesity and type 2 diabetes (T2DM)." (PMID 25689119, 2015).
Umbilical hernia (1 paper, 2018). Protrusion of abdominal contents through a defect in the abdominal wall musculature around the umbilicus. "Targeted sequencing of candidate genes within the region revealed polymorphisms within the Leukemia inhibitory factor (LIF) and Oncostatin M (OSM) that were significantly associated with umbilical hernia (P < 0.001)." (PMID 29843603, 2018).
tumor (140 papers, 2007 to 2026). "We previously showed that oncostatin M (OSM), derived from tumor‐associated macrophages, acts as a major inducer of the upregulation of EMT‐related genes, including LOXL2." (PMID 39297408, 2024). "The activation of hypoxia signaling increases the expression of adipokines, especially the pro-inflammation adipokines (including CCL2, CXCL8, CXCL10, IL-18, IL-1α and Oncostatin M), which is involved in the recruitment of tumor-associated immune cells." (PMID 35350384, 2022). "GRO-α, IL-1β, Oncostatin-M and Leptin, all linked to tumor growth and inflammation, were significantly altered in the IORT group: Leptin increased; GRO-α, IL-1β, oncostatin-M decreased." (PMID 33946741, 2021). "We also analyzed the correlation between OSM expression and the proportion of cancer-associated fibroblasts and endothelial cells, which are known to regulate the tumor immune landscape." (PMID 33216732, 2020). "This gene encodes the pro-inflammatory cytokine OSM, expression of which has been correlated with metastasis of cancer tumours." (PMID 27918443, 2016). "Elevated levels of OSM mRNA isolated from micro-dissected tumor stroma are associated with an increased risk of tumor recurrence, highly aggressive metastatic cancers, and poor patient prognosis." (PMID 24675570, 2014). "Despite the many studies implicating OSM as a suppressor of normal cell and select tumor cell proliferation, OSM has also been implicated, paradoxically, in cancer progression." (PMID 24675570, 2014). "In both tumor types, activation of immune responses was found in cluster 1, and keratinization was a major feature of cluster 2, which was associated with upregulation of oncostatin M, interleukin (IL)-36, and IL-17 signaling." (PMID 38049810, 2023). "The mechanism underlying ING4‐ and OSM‐mediated negative regulation of tumour growth remains largely unknown." (PMID 35075768, 2022). "Loss of OSM function in vivo is associated with a decrease in the level of several inflammatory signals with known pro-tumorigenic function, a shift in the myeloid to MØ infiltration of orthotopic tumours, as well as improved function of APCs and T cells." (PMID 34921158, 2021). "Moreover, the expression of OSM was associated with stromal and immune cell infiltration in the tumor microenvironment, and OSM-related immune checkpoint and chemokine co-expression were also observed." (PMID 34702277, 2021). "Expression of OSM is significantly elevated in the breast, prostate, cervical, and ovarian tumor microenvironments, and several studies provide evidence implicating elevated OSM in metastasis and increased risk of tumor recurrence." (PMID 24675570, 2014). "Mechanistically, high PIM levels increase the recruitment of tumor/inflammation associated macrophages, MDSCs, mast cells, and neutrophils to the target tissue, by increasing IL-6 locally as well as other cytokines (such as OSM) and probably other chemokines (such as CCL2 and CXCL8)." (PMID 28938604, 2017). "This review synthesizes evidence on the roles and molecular mechanisms of major myokines-including IL-6, irisin, SPARC, oncostatin M (OSM), and decorin-in exercise-associated modulation of cancer-related inflammation and tumor progression." (PMID 41983081, 2026). "OSM, as a cytokine, regulates immune evasion and cell migration, enhancing tumor invasiveness and possibly promoting EMT, thereby facilitating metastasis." (PMID 41481587, 2026). "TGF-β1 activates the SMAD3 and ERK1/2 signaling pathways, inducing neutrophils in the tumor microenvironment to express tumor-promoting factors, such as OSM and VEGFA mRNA, thereby converting neutrophils into a pro-tumor phenotype." (PMID 40564191, 2025). "OSM plays a crucial role in TAM-tumor interactions by binding to its receptor, OSMR, on tumor and stromal cells, activating various signaling pathways, including Jak-STAT." (PMID 39286635, 2024).
tumor (continued). "We show that TREM1 myeloid-derived cytokines IL1 and OSM activate the inflammatory NF-κB family of transcription factors within the BIT tumor epithelium and lower the sensitivity of human BCC explant tumors to SMOi treatment, conferring resistance." (PMID 39289380, 2024). "Detailed phenotypic profiling showed that TREM1 myeloid cells were enriched for IL1A, OSM, and IL6 expression compared to other myeloid populations, further supporting the association between BIT tumor epithelium and TREM1 myeloid-derived IL1A and OSM." (PMID 39289380, 2024). "OSM/IL-6/JAK signaling has been reported to support tumor progression by promoting a CSC phenotype and epithelial-mesenchymal plasticity." (PMID 38236642, 2024). "IL1 and OSM secreted by TREM1 myeloid cells activate the inflammatory NF-κB family of transcription factors within the BIT tumor epithelium, leading to transcriptional upregulation of BIT markers." (PMID 39289380, 2024). "Interestingly, several representative genes of tumor-associated neutrophils were highly expressed in OtoNP+ group, including OSM and TREM1, which further suggest that neutrophils might participate in shaping the tumor immune microenvironment by intratumoral translocated microbes." (PMID 38388556, 2024). "TME-derived oncostatin M (OSM) was shown to mediate tumor progression and CSC expansion by activating its receptor, OSMR." (PMID 38236642, 2024). "Tumor-infiltrating neutrophils secrete cytokines, chemokines, reactive oxygen species, and oncostatin M in tumor, and these factors promote tumor progression, angiogenesis, and metastasis." (PMID 39286026, 2024). "Our results provide further support to the importance of this axis in metastatic ccRCC, as OSM expression was expressed in the Macro-1 and Macro-3 populations, while the expression of OSMR was found in tumor-associated MSC-2 cells." (PMID 38281962, 2024). "Tumor neutrophils can release cytokines like oncostatin M, which induces VEGF and increases angiogenesis and tumor cell invasion." (PMID 37398649, 2023). "TANs also promote tumor metastasis by secreting a large amount of the pro-metastatic factor oncostatin M (OSM)." (PMID 37108625, 2023). "Overexpression of OSM in the tumor cells, by adenovirus gene transfer, led to decreased tumor proliferation and enhanced apoptosis in vivo." (PMID 37841259, 2023). "RNA-sequencing revealed that TGF-β1 and TCM alter gene expression in HL-60 cells, including the mRNA levels of the pro-tumor oncostatin M (OSM) and vascular endothelial growth factor A (VEGFA)." (PMID 37682817, 2023). "OSM (Oncostatin-M) is a growth regulator, which inhibits the proliferation of some tumor cell lines and regulates the cytokine production of endothelial cells." (PMID 35419117, 2022). "While the protumoral effect of OSMR activation in cancer cells has been extensively described, little is known about the effects of OSM in the tumor stroma and our results shed light on the effects of OSM signaling in CAFs." (PMID 35192545, 2022). "Human OSM (hOSM) was initially recognized by its activity to inhibit the proliferation of A375 melanoma cells and numerous other tumour cells." (PMID 35075768, 2022). "In summary, our results demonstrate that OSM orchestrates an intriguing protumoral crosstalk between myeloid cells, CAFs, and cancer cells that has important consequences in tumor progression." (PMID 35192545, 2022). "Oncostatin M (OSM) has been reported to be a key regulating factor in the process of tumor development." (PMID 34702277, 2021). "For example, macrophage-derived oncostatin M (OSM) has been revealed to interact with OSMR or LIFR receptors on tumor cells, and induce a mesenchymal-like state transition of GBM cells." (PMID 34805184, 2021). "Since OSM is secreted mostly by myeloid immune cells, we can infer that the high expression of OSM is a consequence of tumor-related inflammation." (PMID 34702277, 2021).
tumor (continued). "These authors associated host-driven inflammation with upregulation of several proliferative pathways found in tumor cells, including transglutaminase-2 and oncostatin M, a member of the IL-6 family." (PMID 34147126, 2021). "Recent researches, on the contrary, elucidate that the overexpression of OSM is closely related to the promotion of tumor progression, including cell proliferation, immunoregulation, angiogenesis, and metastasis." (PMID 34702277, 2021). "We next sought to determine the role of OSM in vivo and analysed the microenvironment of tumours from PCCs38 orthotopically implanted into syngeneic wildtype or Osm-deficient C57BL/6 mice (Osm−/−)." (PMID 34921158, 2021). "Lastly, we sought to determine the pathobiological role of OSM–OSMR signalling on tumour cell function in vivo." (PMID 34921158, 2021). "For instance, some studies have shown that both IL6 and OSM are capable of inducing tumour-promoting effects through STAT3, while IL6, IL11, LIF and OSM can all promote invasion and metastasis through the JAK/STAT3 and PI3K/AKT pathways." (PMID 34834425, 2021). "For instance, the expression of immune-related genes such as interleukin (IL)-6 members, including IL-11, IL-27, IL-31, leukemia inhibitory factor, and oncostatin M (OSM), affect tumor cell proliferation, survival, inflammation, and metabolism." (PMID 34349789, 2021). "Overall, these data suggest that OSM expression regulates the infiltration of immune cells such as DCs, monocytes, and Tfh cells into the tumor microenvironment in CCA tissues." (PMID 33216732, 2020). "For instance, OSM is found to regulate macrophage polarization to a pro-tumor phenotype (M2 type) in the tumor microenvironment, and this regulation is via mTOR signaling complex 2 (mTORC2)." (PMID 31010242, 2019). "As a well-known multifunctional cytokine, OSM has multiple effects and functions, which are important in controlling immune responses, inflammation, cell proliferation, and tumor formation." (PMID 30755233, 2019). "We investigated the involvement of OSM in tumor development by comparing the size of cSCC tumors between OSM-KO mice and their WT littermates." (PMID 30559930, 2018). "We examined whether OSM exerts a direct pro-tumoral activity on cancer cells or has an indirect effect through the activation of cells present in the peritumoral environment by assessing tumor growth in mice deficient for the OSMRβ subunit (OSMR-KO) and their WT littermates." (PMID 30559930, 2018). "Oncostatin M signalling has been previously demonstrated to contribute to tumour progression and metastases through JAK-STAT signalling." (PMID 29339786, 2018). "Neutrophils, as a type of inflammatory cells, are considered to be involved in different steps of tumor development through the production of a variety of cytokines, such as oncostatin M, hepatocyte growth factor, and transforming growth factor- (TGF-) β." (PMID 28321405, 2017). "First, neutrophils, as a type of inflammatory cells, are involved in different steps of tumor development through the production of a variety of cytokines, such as oncostatin M, interleukin-6, hepatocyte growth factor, and tumor necrosis factor." (PMID 29029493, 2017). "Except for OSM, the expression of all anti-tumor genes including TNF-α, PRF1, GZMB, FasL, TNFSF10 and CD40LG were significantly upregulated in CIK cells compared to PBMC, which were negatively correlated with expression profiles of their potential regulators." (PMID 25826780, 2015). "Other anti-tumor genes including OSM, TNF-α and CD40LG were regulated by miRNAs of both downregulated and upregulated." (PMID 25826780, 2015). "We identify HB-EGF and OSM as the key EGFR and STAT3 activators secreted by tumor-primed MΦ, and EREG and OSM as the key activating factors secreted by tumor-primed PBMC." (PMID 23597096, 2013).
tumor (continued). "In our prior studies we identified OSM as a potential driver of STAT3 phosphorylation in canine OS tumor cells and found that inhibition of STAT3 signaling disrupted OSM induced biologic activities." (PMID 23244668, 2012). "Breast cancer cells can stimulate neutrophils to produce oncostatin M, which interacts with tumor cells to lead to the expression of vascular endothelial growth factor (VEGF), thereby augmenting tumor-associated angiogenesis." (PMID 23272179, 2012). "Co-expression of OSM and its receptor was noted in the fresh frozen tumor samples while only OSM receptor was identified in the cell lines." (PMID 21481226, 2011). "Oncostatin M (OSM) is a member of the IL-6 cytokine family produced by inflammatory cells and some tumor cells including primary human osteoblasts and the human OSA cell line MG-63." (PMID 21481226, 2011). "Plasma analyte profiling of both moderately and severely cachectic mice revealed that circulating levels of IL-6 and three other gp130 ligands, IL-11, leukemia inhibitory factor (LIF) and Oncostatin M were significantly increased in tumor-bearing mice." (PMID 21799891, 2011). "OSMR expression was noted in all 8 canine tumor samples evaluated as well as the normal canine osteoblasts while OSM expression was detected in all samples although 2 of these were weak; normal canine osteoblasts did not express OSM." (PMID 21481226, 2011). "Our data demonstrate that the OSM receptor (OSMR), but not IL-6 or its receptor, is expressed by all human and canine OSA cell lines and canine OSA tumor samples; additionally, OSM expression was noted in all tumor samples." (PMID 21481226, 2011). "OSMR is a receptor of Oncostatin M (OSM), an interleukin-6 (IL-6)-type cytokine identified as a potent suppressor of tumor cells." (PMID 19662090, 2009). "Additionally, TDP2-high expression was associated with enriched signaling pathways involved in EMT, including COLLAGEN, GALECTIN, MIDKINE (MK), and ONCOSTATIN M (OSM), which promoted tumor cell migration, invasion, and immune evasion." (PMID 41481587, 2026). "Exercise-induced factor (e.g., irisin, SPARC, oncostatin M), released from contracting skeletal muscles, can exert anti-tumor effects by inhibiting cancer cell proliferation, inducing apoptosis, and reducing angiogenesis within the tumor microenvironment." (PMID 40494940, 2025). "Interestingly, however, the expression of two potentially tumor-promoting genes, OSM and VEGFA, was upregulated in both the TGF-β1- and M4 TCM-treated dHL-60 cells." (PMID 37682817, 2023). "However, in infiltrating carcinomas; high expression of OSMRβ (77.5%) and gp130 (74.1%) proteins have been seen, with OSM localized in 100% of tumor samples studied." (PMID 37841259, 2023). "Indeed, in the TSPO HIGH III cluster we observed a significant overexpression of the MES-like TAM tumor interaction genes OSM, OSMR, STAT3 and of CD44." (PMID 37697350, 2023). "In fact, while OSM expression has been shown to repress tumor growth in some cancer types it also may promote tumor growth in other types." (PMID 37841259, 2023). "In addition, OSM overexpression failed to promote HCC development in TNF-α−/− rats, suggesting that OSM plays a key role in tumor progression, modulating the inflammatory microenvironment." (PMID 36077744, 2022). "OSM is a cytokine that interacts with OSMR as a ligand to induce tumor promotion or inhibition." (PMID 36551576, 2022). "They further identified that TANs also perform autophagy via the synergy of ERK1/2, p38 and NF-κB signaling axis and subsequently facilitate tumor progression by enhancing the secretion of OSM and MMP9, suggesting a regulatory loop between tumor cells and neutrophils." (PMID 36093115, 2022). "As OSM is mainly expressed by myeloid cells, our data point to the existence of a positive feedback loop where OSM signaling induces the recruitment of more myeloid cells that will in turn secrete OSM within the tumor." (PMID 35192545, 2022).